ATF6B (activating transcription factor 6 beta)
Description:
[Cyclic AMP-dependent transcription factor ATF-6 beta]: Precursor of the transcription factor form (Processed cyclic AMP-dependent transcription factor ATF-6 beta), which is embedded in the endoplasmic reticulum membrane. Endoplasmic reticulum stress promotes processing of this form, releasing the transcription factor form that translocates into the nucleus, where it activates transcription of genes involved in the unfolded protein response (UPR). [Processed cyclic AMP-dependent transcription factor ATF-6 beta]: Transcription factor that acts in the unfolded protein response (UPR) pathway by activating UPR target genes induced during ER stress. Binds DNA on the 5'-CCAC[GA]-3' half of the ER stress response element (ERSE) (5'-CCAATN(9)CCAC[GA]-3') when NF-Y is bound to ERSE.
Synonyms: Creb-rp; CREBL1; G13; ATF6beta
Tractability: Antibody: UniProt predicts a signal peptide or a membrane-spanning region. PROTAC: ubiquitination databases record sites on it; its protein half-life has been measured.
Gene: Protein-coding gene on chromosome 6 (32,115,264 to 32,128,253, reverse strand). Ensembl gene ENSG00000213676.
Subcellular location: Endoplasmic reticulum membrane; Nucleus (Processed cyclic AMP-dependent transcription factor ATF-6 beta)
Subcellular location (Human Protein Atlas): Nucleoplasm; Nucleoli
Pathways (Reactome):
Cellular responses to stimuli: ATF6B (ATF6-beta) activates chaperones
Gene Ontology:
Molecular function: DNA-binding transcription activator activity, RNA polymerase II-specific; DNA-binding transcription factor activity; protein binding; RNA polymerase II cis-regulatory region sequence-specific DNA binding; sequence-specific double-stranded DNA binding; transcription cis-regulatory region binding; DNA-binding transcription factor activity, RNA polymerase II-specific
Biological process: negative regulation of ATF6-mediated unfolded protein response; positive regulation of transcription by RNA polymerase II; response to endoplasmic reticulum stress; ATF6-mediated unfolded protein response; endoplasmic reticulum unfolded protein response; regulation of transcription by RNA polymerase II; signal transduction; regulation of ATF6-mediated unfolded protein response; regulation of DNA-templated transcription
Cellular component: endoplasmic reticulum membrane; nucleolus; nucleoplasm; nucleus; protein-DNA complex; RNA polymerase II transcription regulator complex; chromatin; cytosol; Golgi apparatus; Golgi membrane
Genetic constraint (gnomAD): Loss-of-function variants: 50 observed, 84.16 expected, observed/expected ratio (o/e) 0.59, 90% interval 0.47 to 0.75. The upper end of that interval is the gene's LOEUF score, 0.75, which puts it in group 3 of 6, group 1 being the genes least tolerant of losing a copy. Missense variants: 790 observed, 908.2 expected, observed/expected ratio (o/e) 0.87, 90% interval 0.82 to 0.92. Synonymous variants: 344 observed, 370.65 expected, observed/expected ratio (o/e) 0.93, 90% interval 0.85 to 1.01.
Homologues: Orthologues: chimpanzee ATF6B (99% identical), macaque ATF6B (97% identical), mouse Atf6b (88% identical), rat Atf6b (87% identical), dog ATF6B (84% identical), pig ATF6B (81% identical), guinea pig ATF6B (81% identical), rabbit ATF6B (68% identical), tropical clawed frog atf6b (37% identical), Drosophila melanogaster Atf6 (21% identical), Drosophila melanogaster CrebA (10% identical), Caenorhabditis elegans atf-6 (9% identical), and 3 more. Paralogues in human: ATF6 (31% identical), CREB3L3 (13% identical), CREB3L2 (13% identical), CREB3L1 (13% identical), CREB3 (12% identical), CREB3L4 (11% identical), ATF1 (7% identical), CREM (7% identical), CREB1 (7% identical).
Diseases named in the same sentence as ATF6B in open-access papers:
ATF6B is named in the same sentence as 42 diseases in open-access papers, as found by Europe PMC text mining. Sharing a sentence is not in itself a finding about the gene and the disease. The quoted sentences say what the papers report.
breast carcinoma (3 papers, 2018 to 2024). "We found that genetic variants in RPS6KA1, ATF6B, CREB3L1 and SRC genes were associated with modified relationships between reproductive factors and breast cancer, especially the protective effect of the number of deliveries and the early age at menopause." (PMID 29530003, 2018). "In keeping with our results, mutations in SNPs rs1269851 (ATF6B gene) and rs35652107 (CREB3L1 gene) modify the number of births – breast cancer relationship." (PMID 29530003, 2018). "Moreover, increased expression of ATF6B has been correlated with a negative prognosis in patients with breast cancer, supporting our findings." (PMID 38978099, 2024).
cardiac hypertrophy (3 papers, 2019 to 2025). "Instead, we observed that loss of ATF6α or ATF6β initially reduced cardiac hypertrophy but in the long term it accelerated cardiac decompensation and failure after pressure overload." (PMID 30765833, 2019). "We also hypothesized that the reduction in cardiac hypertrophy over 2 weeks due to a presumed alteration or reduction in ER protein production associated with the Atf6 or Atf6b null backgrounds might render these hearts more susceptible to heart failure with chronic hypertrophic stimulation." (PMID 30765833, 2019). "In fact, ATF6β has shown to play overlapping roles with ATF6α in settings of heart hypertrophy." (PMID 37025177, 2023). "Importantly, Atf6b−/− gene-deleted mice appeared to show the same defects in cardiac hypertrophy, mobilization of ER protein chaperones, and ultimately underwent the same accelerated failure with pressure overload as their Atf6−/− counterparts." (PMID 30765833, 2019). "Unexpectedly, we observed that eliminating the Atf6 or Atf6b genes resulted in a significant reduction in cardiac hypertrophy but function was not affected over this relatively short 2 week time period." (PMID 30765833, 2019).
cardiac failure (2 papers, 2019 to 2023). "Moreover, Atf6 or Atf6b null mice, and Atf6+/−Atf6b+/− double heterozygous targeted mice each showed accelerated decompensation and heart failure after long-term (8 week) pressure overload stimulation." (PMID 30765833, 2019).
lung carcinoma (2 papers, 2022). "We have detected the expression of ATF6 and ATF6B in both normal lung tissues and lung cancer tissues." (PMID 35625704, 2022). "The anti-cancer activity of DMC occurs through promoted expression of ER stress-associated proteins HSPA5, DDIT3, ERN1, ATF6A, ATF6B, CASP4 and CAPS12 in human lung cancer NCI-H460 cells." (PMID 36497321, 2022). "Higher expression of ATF6 and ATF6B predicts a better and poorer OS of the lung cancer patients, respectively, indicating a possible tumor suppressor-like activity of ATF6 and an oncogenic property of the ATF6B for lung carcinogenesis." (PMID 35625704, 2022). "BDMC increases ER stress-associated proteins expression such as HSPA5, DDIT3, ERN1, ERN2/IRE-1β, ATF6, ATF6B and CASP4, which results in cell apoptosis in the human lung cancer NCI H460 cell line." (PMID 36497321, 2022). "Although IHC evaluation of the ATF6 and ATF6B in lung cancer tissues vs. case-matched non-cancerous tissues is somewhat inconclusive, the overall survival analysis for the lung cancer patients unraveled an opposite prognostic value between ATF6 and ATF6B." (PMID 35625704, 2022).
prostate carcinoma (2 papers, 2018 to 2024). A carcinoma that arises from epithelial cells of the prostate gland. "These include the endoplasmic reticulum (ER) originating transcription factors CREB3L4 and CREBL1 (also known as ATF6B), which we find are associated with an 14% and 21% increased risk of prostate cancer overall, respectively, and that are expressed in the prostate epithelium." (PMID 38878676, 2024).
Alzheimer disease (1 paper, 2023). A progressive, neurodegenerative disease characterized by loss of function and death of nerve cells in several areas of the brain leading to loss of cognitive function such as memory and language. "MEG3 (ENST00000398461)/hsa-let-7d-5p/ATF6B axis showed importance in Parkinson’s and late Alzheimer’s diseases, while AC092687.3/hsa-let-7e-5p/[SREBF2, FNIP1, PMAIP1] and SDCBP2-AS1 (ENST00000446423)/hsa-miR-101-3p/MAPK6 axes are probably related to Alzheimer’s disease development and pathology." (PMID 38027526, 2023).
ankylosing spondylitis (1 paper, 2024). An autoimmune chronic inflammatory disorder characterized by inflammation in the vertebral joints of the spine and sacroiliac joints. "Among them, AIF1 and IL23R are associated with decreased risk of ankylosing spondylitis; MICA, MAPK14, and ATF6B are linked to increased risk of ankylosing spondylitis." (PMID 38835753, 2024).
atopic dermatitis (1 paper, 2024). "For example, AIF1, MICA, ATF6B, and HSPA1L were found to be associated with an increased risk of rheumatoid arthritis (RA), while AIF1 was also associated with an increased risk of atopic dermatitis." (PMID 38835753, 2024).
bladder cancer (1 paper, 2022). "The TF-protein JUN (a regulator of ANGPT1, HPGD, ATF6B and OAS3) is associated with bladder cancer disease." (PMID 35617355, 2022).
colorectal carcinoma (1 paper, 2020). A malignant epithelial neoplasm that arises from the colon or rectum and invades through the muscularis mucosa into the submucosa. "Here, we used human colorectal carcinoma-derived HCT116 cells deficient in ATF6α and its relevant ATF6β, and found that ATF6α dimer and oligomer are both dimers, which we designated C618-dimer and C467-dimer, respectively." (PMID 31852864, 2020).
epilepsy (1 paper, 2026). A brain disorder characterized by episodes of abnormally increased neuronal discharge resulting in transient episodes of sensory or motor neurological dysfunction, or psychic dysfunction. "The differential expression of four DE‐SRGs between control and epilepsy groups, including IER3, TNF, GPANK1 (upregulated), and ATF6B (downregulated), further elucidates the molecular mechanisms underlying the epilepsy phenotype." (PMID 41466027, 2026). "PCR results show the expression of IER3, TNF, GPANK1, and ATF6B in hippocampus of epilepsy model largely consistent with bioinformatics predictions." (PMID 41466027, 2026). "Although the results of ATF6B in the hippocampus of the PTZ model are different from the transcriptome data, we consider that it is related to the differential expression of ATF6B in different drug‐induced epilepsy models." (PMID 41466027, 2026). "Finally, the expression of four key genes (IER3, TNF, GPANK1, and ATF6B) in the hippocampus of epilepsy mouse model was quantified using PCR." (PMID 41466027, 2026). "Finally, although we validated the altered expression of IER3, TNF, GPANK1, and ATF6B in multiple epilepsy models, we did not investigate the correlation between their expression levels and behavioral seizure outcomes (e.g., Racine scores, seizure frequency)." (PMID 41466027, 2026).
herpes simplex infection (1 paper, 2022). "After treatment of a metastatic BC patient with herpes simplex infection pathway (associated KGs: OAS1, OAS3, ATF6B, IRF9), there has created a case of Sweet Syndrome." (PMID 35617355, 2022).
Insulin resistance (1 paper, 2021). Increased resistance towards insulin, that is, diminished effectiveness of insulin in reducing blood glucose levels. "Therefore, ATF6β could promote the production of adipocytokines, and then the adipocytokines lead to insulin resistance via blocking PI3K-AKT-mediated inhibition of lipolysis attenuating the capacity of glucose utilization." (PMID 35140684, 2021). "Therefore, ATF6β could involve in insulin resistance through PI3K-Akt signaling pathway, which also included the role of TNF-α." (PMID 35140684, 2021).
lung adenocarcinoma (1 paper, 2022). A carcinoma that arises from the lung and is characterized by the presence of malignant glandular epithelial cells. "In both lung adenocarcinoma (AD) and lung squamous carcer (SC), the tumors expressed much higher levels of ATF6B relative to ATF6." (PMID 35625704, 2022).
melanoma (1 paper, 2025). A malignant, usually aggressive tumor composed of atypical, neoplastic melanocytes. "Consistent with our in vitro findings, genes associated with the ATF4 (e.g., ATF4, DDIT3, PPP1R15A and CHAC1), ATF6 (e.g., ATF6B, CALR, SEL1L, and EDEM1) and XBP1 (e.g., SSR3 and DELR1) pathways were significantly enriched in melanoma TILs compared with healthy blood T cells." (PMID 40335738, 2025).
microcephaly (1 paper, 2025). A congenital or acquired developmental disorder in which the circumference of the head is smaller than normal for the person's age and sex. "Here, we report that deletion of activating transcription factor 6 (ATF6), consisting of ATF6α and ATF6β, in the developing brain caused microcephaly and neonatal death in mice." (PMID 40487428, 2025).
periodontal disease (1 paper, 2022). "Considering that ATF6β is an ER stress response-associated gene and emerging evidence has indicated the involvement of ER stress in periodontal disease, we focused on ATF6β in this study." (PMID 36531939, 2022).
periodontitis (1 paper, 2022). An acute or chronic inflammatory process that affects the tissues that surround and support the teeth. "In a mouse periodontitis model, the expression of ATF6β mRNA was upregulated in ligated-gingival tissue." (PMID 36531939, 2022).
prediabetes (1 paper, 2021). "Moreover, the key lncRNA was ENST00000485392 and the corresponding mRNA was ATF6B between prediabetes and normal controls." (PMID 35140684, 2021).
schizophrenia (1 paper, 2023). A major psychotic disorder characterized by abnormalities in the perception or expression of reality. "ATF6B and ATF6, which are activated by the inactive cyclic AMP-dependent transcription factor ATF6 during ER stress, were found to be the predominant DEGs and shared genes between schizophrenia DEGs and ER stress-related genes." (PMID 37376599, 2023). "ATF6 and ATF6B are homologs, so it is not surprising that the ATF6 mRNA level was also increased by 1.3 times in individuals with schizophrenia compared with healthy controls." (PMID 37376599, 2023).
ulcers (1 paper, 2023). "ATF6B and TRAP1 are significantly abundant during the presence of ulcers when compared to the lesion-free groups." (PMID 37170213, 2023). "Due to its ability to distinguish between individuals with and without ulcers, the ATF6B protein raises the possibility that endoplasmic reticulum (ER) stress is responsible for the damage that leads to the death of oral keratinocytes." (PMID 37170213, 2023). "This, accompanied by the high abundance of amyloid-beta precursor protein (APP), apolipoprotein E (APOE), MADD (MAP kinase-activating death domain protein), ATF6B, ERN1 and TRAP1 in the presence of ulcers, shows that, along with cell death, the epithelial health maintenance response is strong." (PMID 37170213, 2023).
cancer (3 papers, 2012 to 2025). A tumor composed of atypical neoplastic, often pleomorphic cells that invade other tissues. "Notably, hsa‐miR‐423‐3p and hsa‐miR‐4286 were upregulated and are known to target cancer‐related genes such as JUNB and members of the AP‐1 family (FOS, FOSL2, ATF‐6B)." (PMID 39575761, 2025).
infection (3 papers, 2016 to 2021). The state of being infected such as from the introduction of a foreign agent such as serum, vaccine, antigenic substance or organism. "ATF6β-deficient mice exhibit a high susceptibility to infection by the parasite, indicating that ATF6β has a key role in resistance against T. gondii infection." (PMID 28883998, 2017). "Previous studies have shown that ectopic expression of ROP18 kinase activity in the absence of infection and PVM formation mediated the degradation of host NF-κβ as well as host ATF6β." (PMID 27447180, 2016).
tumor (3 papers, 2020 to 2026). "Mechanistically, IMMT loss promotes ATF6α-ATF6β heterodimer formation, whereby ATF6α stabilizes ATF6β protein, enabling ATF6β to engage PPARγ through direct physical interaction and orchestrate redox homeostasis remodeling that sustains tumor cell proliferation." (PMID 42049712, 2026). "ATF6 may more likely tend to be a tumor suppressor, whereas ATF6B appears to be more oncogenic." (PMID 35625704, 2022). "The differences in the prognostic values between ATF6 and ATF6B are also reflected by the different expression levels of these two ATF6 genes between normal lung tissue and tumor tissues." (PMID 35625704, 2022).
ATF6B also shares sentences with these, for which no sentence is quoted: Anxiety (1 paper); chylomicron retention disease (1); familial lipoprotein lipase deficiency (1); fatty liver disease (1); glaucoma (1); glioblastoma (1); hyperglycaemia (1); lung (1); meningioma (1); Obesity (1); Parkinson (1); primary sclerosing cholangitis (1); respiratory disorders (1); rheumatoid arthritis (1); sarcopenia (1); senile cataract (1); sweet syndrome (1); type 1 diabetes (1).